ACBD7 (acyl-CoA binding domain containing 7)
Description:
Binds medium- and long-chain acyl-CoA esters.
Synonyms: FLJ38219; bA455B2.2
Tractability: Small molecule: a structure with a bound ligand is known.
Gene: Protein-coding gene on chromosome 10 (15,075,475 to 15,088,776, reverse strand). Ensembl gene ENSG00000176244.
Subcellular location (Human Protein Atlas): Cytosol; Vesicles
Pathways (Reactome):
Metabolism: Mitochondrial Fatty Acid Beta-Oxidation
Gene Ontology:
Molecular function: protein binding; fatty-acyl-CoA binding
Biological process: fatty acid metabolic process
Genetic constraint (gnomAD): Loss-of-function variants: 11 observed, 11.94 expected, observed/expected ratio (o/e) 0.92, 90% interval 0.58 to 1.51. The upper end of that interval is the gene's LOEUF score, 1.51, which puts it in group 6 of 6, group 1 being the genes least tolerant of losing a copy. Missense variants: 96 observed, 91.45 expected, observed/expected ratio (o/e) 1.05, 90% interval 0.89 to 1.24. Synonymous variants: 42 observed, 35.41 expected, observed/expected ratio (o/e) 1.19, 90% interval 0.93 to 1.53.
Homologues: Orthologues: chimpanzee ACBD7 (98% identical), macaque ACBD7 (95% identical), chimpanzee ACBD7 (93% identical), dog ACBD7 (86% identical), pig ACBD7 (84% identical), guinea pig ACBD7 (83% identical), mouse Acbd7 (83% identical), rat Acbd7 (83% identical), zebrafish acbd7 (68% identical), Drosophila melanogaster Acbp1 (57% identical). Paralogues in human: DBI (61% identical), ECI2 (42% identical), ACBD4 (38% identical), ACBD5 (35% identical).
Diseases named in the same sentence as ACBD7 in open-access papers:
ACBD7 is named in the same sentence as 7 diseases in open-access papers, as found by Europe PMC text mining. Sharing a sentence is not in itself a finding about the gene and the disease. The quoted sentences say what the papers report.
Obesity (3 papers, 2016 to 2021). Accumulation of substantial excess body fat. "Recent studies have linked the gene that encodes a protein called ACBD7 with obesity, and showed that it is one of the genes that is overexpressed in neurons that are sensitive to leptin." (PMID 26880548, 2016). "Acyl-CoA binding domain-containing 7 (Acbd7) is a paralog gene of the diazepam-binding inhibitor/Acyl-CoA binding protein in which single nucleotide polymorphism has recently been associated with obesity in humans." (PMID 26880548, 2016). "ACBD7 could be involved in energy homeostasis and associated to obesity in humans." (PMID 33522899, 2021).
bacterial meningitis (1 paper, 2024). Inflammation of the membranes surrounding the brain and spinal cord due to a bacterial infection. "In bacterial meningitis patients, 8 co-expression relationships were constructed between 8 mRNAs (ACBD7, OR52K2, GPR68, SHISA4, KIF5C, OR52P2P, OR51R1P, and CCR5) and 1 lncRNA." (PMID 38347610, 2024).
breast carcinoma (1 paper, 2024). "ACBD3, from the same family as ACBD7, has been found to be up-regulated in a variety of tumor tissues and may be responsible for poor breast cancer prognosis." (PMID 38329437, 2024).
morbid obesity (1 paper, 2016). An excess of body weight, normally defined as an individual with a body mass index greater than 35 or a body weight greater than one hundred percent of ideal body weight. "Additionally, it is noteworthy that single nucleotide polymorphism in both the DBI/ACBP and ACBD7 are linked with morbid obesity in humans, suggesting that these two genes are complementary involved in the hypothalamic regulation of energy balance." (PMID 26880548, 2016).
cancer (1 paper, 2024). A tumor composed of atypical neoplastic, often pleomorphic cells that invade other tissues. "ACBD7 can be regulated by transcription factors to promote muscle development and lipid metabolism, but cancer-related studies are lacking." (PMID 38329437, 2024).
ACBD7 also shares sentences with these, for which no sentence is quoted: tumor (2 papers); thyroid cancer (1).